AR (androgen receptor)
Diseases named in the same sentence as AR in open-access papers (continued):
Sharing a sentence is not in itself a finding about the gene and the disease.
atherosclerosis (21 papers, 2011 to 2025). A disease characterized by the build-up of fatty material and calcium deposition in the arterial wall resulting in partial or complete occlusion of the arterial lumen. "Consistent with other atherosclerosis-associated cell types, platelets express the androgen receptor, and androgen levels influence platelet activity." (PMID 39639392, 2024). "NFE2L2 is associated with atherosclerosis, AR is associated with coronary artery disease, and PTGS2 is associated with myocardial infarction." (PMID 36188612, 2022). "A reduced number of monocytes and macrophages in ARKO mice indicates that AR is involved in the modulation of inflammation, including inflammatory-associated atherosclerosis." (PMID 33514065, 2021). "In the present study, we found that AR deficiency increased serum lipid levels and atherosclerosis in female mice, whereas AR stimulation exerted the opposite actions." (PMID 25550469, 2015). "To determine the physiologic androgen receptor (AR)–dependent actions of androgens on atherogenesis in female mice, we generated female AR-knockout (ARKO) mice on an atherosclerosis-prone apolipoprotein E (apoE)–deficient background." (PMID 25550469, 2015). "Activation of the AR has been linked to increased cardiac hypertrophy, atherosclerosis, myocarditis/DCM and heart failure in male mice and humans." (PMID 21338512, 2011). "Testosterone supplementation reduced atherosclerosis in both androgen-receptor knockout mice on apolipoprotein E-deficient background and wild-type mice but the extent of atheroprotection of testosterone was lower in androgen-receptor knockout mice." (PMID 39639392, 2024). "Using models of androgen receptor deficiency, the testicular feminized mouse, and androgen receptor deletion mouse models, two separate studies distinguished androgen receptor-dependent mechanisms from effects because of aromatization of testosterone to estradiol in a mouse model of atherosclerosis." (PMID 37999647, 2024). "Murine studies suggest that androgen deprivation worsens atherosclerosis, inducing larger atherosclerotic lesions in orchiectomized mice and in androgen receptor knockout mice compared to sham-treated and wild-type mice, respectively." (PMID 39639392, 2024). "Regarding atherosclerosis, high levels of AR signaling can lead to changes in blood lipid profiles in the body, increased inflammation in endothelial cells, increased muscle cell proliferation, and changes in platelet activity." (PMID 37571268, 2023). "Due to gender differences in the incidence of atherosclerosis between males and females, investigation into the effect of supra-physiological doses of androgens and AR signaling on atherosclerotic development has been conducted." (PMID 37571268, 2023). "Hormone receptor (AR, ERα, and ERβ) promoters’ methylation is involved in the development of many diseases, such as atherosclerosis, endometriosis, and cancer." (PMID 35203670, 2022). "By using statistical and system biology approaches, we show that gene expression of the plaque tissue of men with severe atherosclerosis is unrelated to plasma testosterone levels, despite a high relative expression of the androgen receptor." (PMID 34195238, 2021). "On the other hand, animals with deletion of AR in macrophages/monocytes are protected from atherosclerosis and depletion of AR has protective effects on abdominal aortic aneurysm development in WT mice." (PMID 32849566, 2020). "In conclusion, we demonstrate that the AR confers protection against diet-induced atherosclerosis in female mice and propose that this is mediated by modulation of body composition and lipid metabolism." (PMID 25550469, 2015). "To determine the physiologic AR-dependent actions of androgens on the development of atherosclerosis in females, we generated female ARKO and control mice on an atherosclerosis-prone apolipoprotein E (apoE)–deficient background." (PMID 25550469, 2015).
atherosclerosis (continued). "In one recent study for instance, the role of the androgen receptor (AR) on atherosclerosis was studied in mice." (PMID 22518131, 2012). "Atherosclerosis in AR knockouts was compared to wild type confirming the presence of both an AR-dependent and an AR-independent pathway for atheroprotection by testosterone." (PMID 22518131, 2012). "Additionally, androgen receptor gene knockout in female mice has been shown to exacerbate diet-induced atherosclerosis in the aorta, suggesting a protective role for androgen receptor signalling in cardiovascular health." (PMID 40136716, 2025). "Another way that AR signaling may contribute to atherosclerosis is through the potential formation of pro-inflammatory cytokines, such as IL-1α, which may contribute to the formation of plaques under supra-physiological androgen doses." (PMID 37571268, 2023). "In alleviating atherosclerosis, targeting AR may yield better results than interfering with androgen expression because androgen deficiency leads to an elevated lipid profile." (PMID 35571620, 2022). "Taken together, these observations seem to indicate that AR disruption may play some role in promoting atherosclerosis." (PMID 33514065, 2021). "After 8 weeks on a high-fat diet, but not on a normal chow diet, atherosclerosis in aorta was increased in ARKO females (+59% vs. control apoE-deficient mice with intact AR gene)." (PMID 25550469, 2015). "By contrast, a number of studies in ovariectomized female mice showed atheroprotection by testosterone, and similar to our findings, 1 study showed that the nonaromatizable AR agonist DHT protected against atherosclerosis in female apoE-deficient mice, supporting the importance of the AR." (PMID 25550469, 2015). "Differences in atherosclerosis, body weight, and lipid levels between ARKO and control mice were abolished in mice that were ovariectomized before puberty, consistent with a protective action of ovarian androgens mediated via the AR." (PMID 25550469, 2015). "Future investigations should try to determine whether androgens inhibit atherosclerosis through direct modulation of non-vascular AR or following conversion to oestrogens." (PMID 24903497, 2014). "The increased testosterone levels are unlikely to contribute to the increased atherosclerosis in the ARKO females; testosterone should have mainly estrogenic effects in the absence of the AR, and exogenous testosterone reduces atherosclerosis in apoE-deficient females." (PMID 25550469, 2015).
neuroendocrine tumors (21 papers, 2019 to 2026). "For example, NSD2 inhibition restores androgen receptor expression and re-sensitizes neuroendocrine tumors to enzalutamide." (PMID 41601922, 2026). "In contrast, second-generation antiandrogens have been reported to promote genetic abnormalities in CRPC cells, leading to increased AR activity and the conversion of cancer cells to neuroendocrine tumors." (PMID 37118708, 2023). "Although a recent study showed that majority of AR-positive neuroendocrine tumors also express NKX3.1, which is consistent with its origin as an AR-regulated gene." (PMID 34625072, 2021). "Although the relationship between neuroendocrine tumor and PCa remains to be elucidated, people have decades of clinical experience of PCa treatment, that will help us confront AR positive NBs." (PMID 34041015, 2021). "Based on histopathology, there are three main groups of PDXs: adenocarcinomas (55%), neuroendocrine tumors (31%), and those with mixed pathology that are positive for both the AR and neuroendocrine markers to varying degrees (14%)." (PMID 34413304, 2021). "One explanation was that neuroendocrine tumor cells were resistant to hormonal therapies that target AR signaling." (PMID 33598420, 2020). "The development of more potent second-generation anti-androgens has led to an increase in non-neuroendocrine tumours that are independent from AR pathway activity." (PMID 31551480, 2019). "Several mechanisms and signaling pathways have been found to be implicated in ENZA resistance of PC, for example, the alterations of the AR, transdifferentiation to neuroendocrine tumors, glucocorticoid receptor overexpression, DNA‐repair and PI3K pathway alterations." (PMID 35689436, 2022). "In addition, there are reports of atypical neuroendocrine tumor cells that coexpress AR target genes and neuroendocrine markers." (PMID 36317634, 2022). "Significantly lower PSA serum levels in AR-V7neg compared to AR-V7pos patients support the hypothesis of an AR-independent, yet emerging neuroendocrine tumor phenotype 21." (PMID 32685010, 2020). "PDX 305R was derived from a radical prostatectomy specimen obtained from a patient who died rapidly from their disease; it is a de novo large cell neuroendocrine tumor negative for AR and expressing markers of neuroendocrine differentiation." (PMID 39117800, 2024). "Although the function of AR in neuroblastoma cells were investigated in the previous work, the expression of AR and other proteins in AR-SCAP-SREBPs-CYP17A1/HMGCR Axis had never been examined in clinical samples of neuroblastoma or other types of neuroblastic or neuroendocrine tumors." (PMID 34041015, 2021). "Interestingly, the use of the AR signalling inhibitors enzalutamide and abiraterone increased the number of non-neuroendocrine tumours that are independent of AR pathway activity to more than 20% of CRPC patients." (PMID 31551480, 2019).
prostatic intraepithelial neoplasia (21 papers, 2011 to 2025). "This is contrary to the findings that a loss of stromal AR diminished the development of prostatic intraepithelial neoplasia lesions." (PMID 25793207, 2015). "Reduced AR expression was observed in stromal cells surrounding prostate intraepithelial neoplasia (PIN) and PCa lesions." (PMID 39369165, 2024). "Apart from loss of Nkx3.1 a decrease in Pten specifically in the prostate, sustained androgen receptor expression, increased Myc and Sox9 also promote early stages prostatic intraepithelial neoplasia." (PMID 23786676, 2013). "Functional AR is expressed at any stage of PCa including prostate intraepithelial neoplasia (PIN), primary PCa, and metastatic PCa before and after androgen-ablation therapy." (PMID 22737441, 2011). "Whatever the case, many studies support an oncogenic role for stromal AR, which might induce prostatic intraepithelial neoplasia (PIN; 96) or even metastatic events." (PMID 35222290, 2022). "Similarly, the spontaneous development of prostatic intraepithelial neoplasia seen in PTEN+/− mice, was decreased in offspring bred with stromal AR knockout mice (ARKO)." (PMID 28117763, 2017). "Furthermore, in vivo studies have demonstrated that PTEN(+/−) mice lacking macrophage AR develop fewer prostatic intraepithelial neoplasia lesions, supporting an important role for macrophage AR signaling during prostate tumorigenesis." (PMID 30871130, 2019).
heart failure (20 papers, 2008 to 2025). Inability of the heart to pump blood at an adequate rate to meet tissue metabolic requirements. "The association between the α2CDel322-325 AR polymorphism and heart failure is biologically plausible, as sustained cardiac adrenergic stimulation has been implicated in the development and progression of heart failure." (PMID 18320080, 2008). "MT reduced the upregulation of AR and endothelial nitric oxide synthase proteins following heart failure." (PMID 39041001, 2024). "These core TFs include MITF (TF for aging DEGs in macrophage, fibroblast, and pericyte), a gene linking to the hypertrophic response, and AR (TF for aging DEGs in CM, macrophage, and fibroblast), a key molecular target to treat heart failure." (PMID 37084237, 2023). "Since alterations inβ-AR mechanisms are reported in heart failure, these targets have beenmanipulated to achieve clinically relevant therapies." (PMID 39076390, 2023). "Although the β,1-adrenoreceptor (AR) Gly389Arg and α2C-AR Del322-325 gene variants are associated with the response to β-AR-blocker therapy, whether this effect is associated with the risk for heart failure, or the severity or progression of heart failure is uncertain." (PMID 18776959, 2008). "Elevated testosterone levels in men might result in a more potent activation of the AR, potentially explaining the divergent clinical trajectories of heart failure between genders." (PMID 37998524, 2023). "Moreover, STR and AR also exhibited remarkable anti-heart failure activity in most cardiac function indicators." (PMID 36278179, 2022). "STR, AR and GRR, as well as the components of A-STR, F-AR and F-GRR also had excellent anti-heart failure activity." (PMID 36278179, 2022).
metabolic syndrome (20 papers, 2011 to 2025). A cluster of metabolic risk factors for CARDIOVASCULAR DISEASES and TYPE 2 DIABETES MELLITUS. "DHT‐treated mice with a neuron specific deletion of AR exhibit partially rescued ovulatory function, protection from adipocyte hypertrophy and ameliorated dyslipidemia." (PMID 35267218, 2022). "Several cohort and cross section studies have shown an association between lower serum testosterone (a principal male sex hormone which binds to the androgen receptor) levels and a higher metabolic syndrome percentage and cardiovascular morbidity." (PMID 35763533, 2022). "It isinteresting that the mean levels of the androgen receptor are elevated in theobese group and decreased in the metabolic syndrome group." (PMID 22442648, 2011). "In turn, androgen receptor-knockout mice exposed to a high-fat diet were found to be characterized by the earlier development of atherosclerotic changes in the aorta, impaired insulin sensitivity, and atherogenic dyslipidemia in comparison to control mice with the intact androgen receptor gene." (PMID 40290009, 2025). "Although these hormonal changes may correlate with previously characterized metabolic syndromes, it is possible that changes during preimplantation and postimplantation development directly influence gene expression pathways involved in testosterone production and AR regulation." (PMID 40036079, 2025). "Androgen receptor signalling is involved in the maintenance of diversity of gut microbiota; androgen-receptor knock-out mice experienced HFD-induced metabolic syndrome and gut dysbiosis, but intervention of the gut microbiome by antibiotics prevented metabolic syndrome." (PMID 36900168, 2023).
partial androgen insensitivity syndrome (20 papers, 2012 to 2025). "Trio‐ES revealed a known pathogenic hemizygous splicing variant in the AR gene (NM_000044.4): c.2667C>T (p.Ser889=), consistent with the diagnosis of partial androgen insensitivity syndrome." (PMID 33942428, 2021). "Partial androgen insensitivity syndrome (PAIS) results from mutations in the androgen receptor gene and is characterized by a wide range of phenotypes." (PMID 41283580, 2025). "Partial androgen insensitivity syndrome (PAIS) is associated with impaired male genital development and can be transmitted through mutations in the androgen receptor (AR)." (PMID 22518120, 2012). "Although partial androgen insensitivity syndrome (PAIS) is caused by attenuated responsiveness to androgens, androgen receptor gene (AR) mutations on the coding regions and their splice sites have been identified only in <25% of patients with a diagnosis of PAIS." (PMID 29396419, 2018). "In boys with suspected partial androgen insensitivity syndrome (PAIS), systematic evidence that supports the long-term prognostic value of identifying a mutation in the androgen receptor gene (AR) is lacking." (PMID 27403927, 2016).
Hepatic steatosis (19 papers, 2013 to 2024). Steatosis is a term used to denote lipid accumulation within hepatocytes. "It revealed a greater degree of hepatic steatosis and inflammation in hepatic androgen receptor (AR) knock-out mice, 5α-reductase type 1 knock-out mice and testicular feminised mice with non-functional AR and low circulating testosterone levels." (PMID 34552789, 2021). "Liver AR knockdown, or AR inhibitors can attenuate hepatic steatosis and related metabolic disorders in mice." (PMID 34867414, 2021). "Disruption of hepatic AR also predisposes male but not female mice to hepatic steatosis, emphasising the important role of androgens in metabolic regulation within liver, the major site of 5αR1 expression." (PMID 27647861, 2017). "In contrast, the role of AR in hepatic steatosis is less controversial." (PMID 26491440, 2015). "Hepatic AR-knockout (H-AR−/y) male (but not female) mice on a HFD diet also developed hepatic steatosis as a result of a rise in SREBP-1c and PPAR-γ." (PMID 32290381, 2020). "However, other two global ARKO mouse models do not show hepatic steatosis, possibly a consequence of different AR targeting strategies adopted and of the genetic background of the mice." (PMID 34572151, 2021). "In support of this, dual brain-adipocyte AR knock-out, but not brain-specific AR knock-out, in a PCOS-like mouse model completely protects against both hepatic steatosis and parametrial adipocyte hypertrophy." (PMID 39345868, 2024).